IL11 (interleukin 11)
Diseases named in the same sentence as IL11 in open-access papers (continued):
Sharing a sentence is not in itself a finding about the gene and the disease.
tumor (continued). "Bone resorption promoted by tumor cells (secretion of PTHrP, IL-11, CTGF, CXCR4, MMP-1) releases factors that stimulate tumor cells themselves, establishing a positive feedback mechanism (vicious cycle) that results in the spread of bone metastatic disease." (PMID 34212564, 2021). "Downstream molecules of the TGF-β signaling pathway related to tumor metastasis, including ANGPTL4 and IL11, were also significantly upregulated in SE than SN patients." (PMID 34557402, 2021). "To determine if MAFF and its downstream targets, IL11/STAT3, play a significant role in tumor metastasis, we performed in vivo experiments using MDA-MB-231 cells injected into the mammary fat pad of NSG mice." (PMID 34262028, 2021). "For instance, CAFs secrete growth factors such as CXCL12, HGF, EGF, IGF, IL‐6, IL‐8, IL‐11 and CCL5, which facilitate tumour growth." (PMID 33943003, 2021). "Tumor tissues exhibited significant colocalization of MAFF and HIF-1 (66% colocalization), MAFF and IL11 (94% colocalization), and BACH1 and IL11 (75% colocalization), suggesting their interactive role in cancer." (PMID 34262028, 2021). "After a series of validation experiments for the concerned genes, it was found that IL6, GM‐CSF (CSF2), IL11, CCL3, S100A8 and S100A9 were significantly decreased in the gut tumours of ApcMin/+ TLR4−/− mice compared with ApcMin/+ WT mice." (PMID 31650683, 2020). "But, in cancer, TGF-β/SMAD signaling promotes the secretion of IL-11 by CAFs, which triggers GP130/STAT3 signaling in tumor cells, increasing the efficiency of tumor metastasis formation." (PMID 33322749, 2020). "A prognostic signature based on RGs (AGTR1, CTGF, FAM3B, IL11, IL17C, PTH2R and SPAG11A) performed moderately in prognostic predictions and correlated with age, tumor stage, metastasis, number of lesions, and tumor burden." (PMID 30661062, 2019). "IL11/GP130 signaling plays a critical role in tumorigenesis, tumor proliferation metastasis and chemoresistance in multiple types of cancers." (PMID 30736824, 2019). "They identify IL-11 as a key factor that increases after surgery and show that blocking of STAT3 signaling induced by IL-11 reduces proliferation of the tumor cells and, eventually, HCC." (PMID 31683891, 2019). "Despite the sensitivity of destabilizing IL11 and SERPINE2 mRNAs in response to tumor hypoxia, YTHDF2 expression is readily silenced in the presence of active HIF-2α." (PMID 31735169, 2019). "In most studies using CAF coculture methods, tumor cells obtained CDDP resistance through CAF-secreted chemokines or growth factors, such as interleukin (IL)-6, IL-8, IL-11, insulin-like growth factor 1, or transforming growth factor-β (TGF-β)." (PMID 31450627, 2019). "HEGBC promotes GBC cell proliferation and migration, inhibited GBC cell apoptosis, and promoted tumor growth and metastasis of GBC via forming a positive regulatory loop with IL-11/STAT3." (PMID 30086773, 2018). "In this report, we investigated the regulation and function of IL11 in high grade, G3-derived AN3CA endometrial epithelial cells in vitro and in vivo in xenograft tumours in mice." (PMID 28186993, 2017). "IL-11, a downstream target of PTGS2 and a potent driver of tumor progression in CAC, was significantly reduced in inflamed MDR1A KO tumors compared to WT tumors." (PMID 28686677, 2017). "In AN3CA tumour tissue, immunohistochemistry demonstrated that STAT3 is phosphorylated under basal conditions and exogenous IL11 further enhanced this (p < 0.05)." (PMID 28186993, 2017). "Lastly, metastasis virulence genes, such as parathyroid hormone-related protein (PTHRP) and interleukin 11 (IL11) enable tumor cells to colonize and survive at the distant secondary tumor site." (PMID 27600078, 2016). "Among them, we selected five decreased (CCDC28B, SREK1IP1/P18SRP/SFRS12IP1, RASL10B, PHF21A/BHC80 and PGC) and two increased genes (IL-11 and CXCL2), by microarray, as differentiation-, splicing-, inflammation-, or tumor-related genes." (PMID 26701885, 2016).
tumor (continued). "The mechanisms how IL-22 confers stemness in tumor cells compared with other pro-tumorigenic cytokines also signaling through STAT3, such as IL-6 and IL-11, warrant further investigation." (PMID 27148488, 2016). "In this context, we demonstrated in tumor biopsies that halofuginone inhibits the expression of RANKL and IL-11 mRNA, two TGF-β target-cytokines that play a central role in bone osteolysis." (PMID 26015407, 2015). "However, the role of IL-11 in MDSCs in tumour microenvironments is unknown." (PMID 28781374, 2015). "IL-11 as well as IL-6 activates STAT3, which is closely related to growth, differentiation and metastasis of cancer cells in the tumour microenvironment." (PMID 28781374, 2015). "Recent studies demonstrate that miR-30c, one of the well-known tumor suppressor miRNAs that promote cell death and inhibit tumor invasion, plays an important role in reversing chemotherapy resistance by regulating TWF1 and interleukin-11." (PMID 26526790, 2015). "We conclude that IL-1 signaling antagonizes IL-11/STAT3 mediated pathology and the genetic deletion of IL-1RT1 results in increased tumor burden." (PMID 25528766, 2015). "The combination of IL-11 and RGD agents clearly demonstrated the possibility to detect the tumor mass containing Her-2-negative cells." (PMID 23331017, 2013). "Other tumor-derived cytokines and cell surface/ECM proteins like bone morphogenetic protein (BMP), interleukin-11 (IL-11), osteopontin (OPN), and endothelin-1 participate and feed this vicious cycle." (PMID 22482058, 2012). "Plasma analyte profiling of both moderately and severely cachectic mice revealed that circulating levels of IL-6 and three other gp130 ligands, IL-11, leukemia inhibitory factor (LIF) and Oncostatin M were significantly increased in tumor-bearing mice." (PMID 21799891, 2011). "The ability of HA to modulate the molecular interplay involved in tumor-mediated bone osteolysis was next tested by examining VEGF, PTHrP, IL-11, and IL-8 as specific examples of tumorigenic and pro-osteoclastic factors." (PMID 20107512, 2010). "Importantly, it is also found that IL‐11 expression is elevated in human TNBC tissues and negatively correlated with the number of NK cells in the tumor microenvironment." (PMID 41178513, 2026). "H3K9la enhances the expression of interleukin-11 (IL-11), which subsequently triggers immune checkpoint activation through the JAK2/STAT3 signaling pathway, ultimately impairing CD8+ T cell activity and facilitating tumor growth." (PMID 41491598, 2026). "Additionally, DIC modulates key tumor microenvironment factors, including VEGF-A, MMP-9, IL-11, and CXCL-12." (PMID 41827705, 2026). "Furthermore, lncRNA-ATB promotes the autocrine induction of IL-11 by binding to IL-11 mRNA, activating the STAT3 signaling pathway, and further facilitating the organ colonization of disseminated tumor cells." (PMID 40352941, 2025). "This approach highlighted several putative iCAF-enriched populations from both normal and tumour samples; in normal tissues these included Stress-response Fib, CXCL8 + Breast Fib and universal (PI16+) fibroblasts; in tumours, IL11 + CAF, IGF1 + CAF and proto-CAF." (PMID 39757146, 2025). "The IL‐11/IL‐11RA axis emerges as a critical driver of LUAD tumourigenesis, exerting its effects through enhanced tumour cell proliferation and remodelling of the tumour microenvironment." (PMID 40673604, 2025). "Specifically, IL-11 activates STAT3 phosphorylation, which inhibits IFNγ-induced STAT1 phosphorylation, thereby downregulating MHC-I and CXCL9 expression in tumor cells and impairing CD8+ T cell infiltration—promoting immune evasion and tumor growth in CRC." (PMID 41359051, 2025). "Overall, the immune profiling analysis indicates that high levels of IL‐11 may modulate the TME, skewing the immune cell infiltration, promoting immune evasion and impairing the anti‐tumour response." (PMID 40673604, 2025).
tumor (continued). "Moreover, the IL-11-overexpressing subclone facilitated increased tumor growth in the presence of LOXL3, indicating that LOXL3-overexpressing cells benefited from the IL-11-overexpressing cells." (PMID 39774289, 2025). "At the same time, STAT3 upregulates the expression of lncRNAs by binding to their promoters, forming lncRNA/IL-6/STAT3 or lncRNA/IL-11/STAT3 loops, which enhance the drug resistance of tumor cells, or promoting tumor growth and metastasis in vivo and inhibiting tumor cell apoptosis." (PMID 38172648, 2024). "Consistent with the results from non-tumor samples, all the TIMGs that we identified (ENO1, MUC1, COL5A1, COL11A1, IL11, AIM2, JUNB) as well as FABP7, exhibited significantly or moderately elevated expression in multiple TCGA tumors, including GBM, compared to normal tissues." (PMID 39596296, 2024). "In particular, IL-11 has been shown to be critical to disease onset and progression in the gp130Y757F IGC model and can be therapeutically manipulated to prevent and reverse tumor progression." (PMID 38542101, 2024). "However, we used I5270, an antibody that neutralizes human IL11, to verify the inhibition of EGFR phosphorylation and PDL1 expression in tumor cells in vitro." (PMID 38696655, 2024). "IL11 functions as a ligand of EGFR, and this binding activates EGFR and downstream signaling to increase the expression of PDL1, culminating in the immune escape of tumor cells." (PMID 38696655, 2024). "Furthermore, a cytokine array analysis showed increased Il33 and Cst3 expression in both tumor and serum from KPC-Cdh11+/+ mice compared to KPC-Cdh11+/- mice, while Il11 was highly enriched in KPC-Cdh11+/+ serum alone and Ccl11 was enriched in tumor alone." (PMID 37954069, 2023). "In addition, the interaction between lncRNA ATB and IL-11 mRNA triggers the STAT3 signal, which can promote tumour cell colonization in organs." (PMID 36447000, 2023). "IL11-induced secretome in primary cultures of human kidney, lung or skin fibroblasts comprises several SASP factors, including IL6, IL8 and CCL20, which are also important in the tumor microenvironment." (PMID 36980201, 2023). "CAFs in GC have been found to secrete cytokines, such as CXCL12, interleukin 11 (IL-11), stromal-derived factor 1 (SDR1), and fibroblast growth factor 9 (FGF-9), to promote epithelial–mesenchymal transition (EMT), the key initiator of tumor invasion and metastasis." (PMID 35557959, 2022). "Multiple studies have relied on mass spectrometry to identify protein biomarkers in NSCLC tumor tissue but IL11 was not identified as a differentially expressed protein." (PMID 35883698, 2022). "Clinical results have shown that myCAFs have a synergistic effect on T cells and inhibit tumor growth, while inflammatory CAFs promote tumor growth and immunosuppressive response by secreting ECM proteins and cytokines such as IL-6, IL-11 and leukemia suppressors." (PMID 35965504, 2022). "Taken together, these early studies suggest that IL11 was more likely an inhibitor, rather than a stimulator, of tumor growth." (PMID 35883698, 2022). "Several tumor cells including BrCa and PrCa cells as well as local cells of the TME such as adipocytes, macrophages, or osteoblasts are able to produce IL-6, IL-8, and IL-11." (PMID 34064859, 2021). "We also found similar effects of trametinib on tumors of the small intestine in ApcMin/+ mice, although the decrease in Il11 expression in response to trametinib was not statistically significant." (PMID 33863879, 2021). "In contrast to BACH1, NRF2 knockdown in MDA-MB-231 did not affect IL11 expression or tumor cell invasion, since it is already low in expression." (PMID 34262028, 2021). "An important number of cytokine levels were below the detection limit of the method (LOD and/or LLOQ) such as IL-2, IL-10, IL-11, IL-12 (p40), IL-12 (p70), IL-19, IL-27 (p28), IL-28A/IFN-λ2, IL-29/IFN-λ1, IFN-α2 and osteocalcin in both tumor and normal tissue control samples." (PMID 33846436, 2021).
tumor (continued). "BM transfer experiments revealed that IL-11+ fibroblasts critically contributed to tumor progression and that IL-11+ fibroblasts were not derived from BM." (PMID 33863879, 2021). "In addition, it induces IL-11 autocrine by binding to IL-11 mRNA and triggers STAT3 signaling, which promotes the histochemistry of metastatic tumor cells." (PMID 34869051, 2021). "In addition, interleukin-6 (IL-6), interleukin-11 (IL-11), and tumor necrosis factor alpha (TNF-α) produced in tumor cells also enhance osteoclast formation and activation or osteoclast precursor activation." (PMID 33672879, 2021). "In addition, m6A modification can also regulate the expression of VEGFA through the miR-143-3P/VASH1 axis, as well as through the regulation of SERPINE2, IL11, and HDGF stability, thus affecting tumor angiogenesis." (PMID 33926508, 2021). "In our tumor series, miR-20a-5p expression was correlated to TTBM, inversely correlated to the expression of the BM protective gene OPG and correlated to the expression of several genes involved in BM (RUNX2, TCF7 and IL11)." (PMID 33800656, 2021). "Furthermore, human microglia can promote TMZ resistance by the augmented expression of inflammatory IL-11, which activates the STAT3 (signal transducer and activator of transcription 3)-MYC pathway in tumor cells." (PMID 34646780, 2021). "Together, these results suggest that most IL-11+ cells are not likely derived from BM cells, but that IL-11− cells became IL-11+ cells during tumor development." (PMID 33863879, 2021). "Indeed, among several cytokines that regulate the tumor-bone interaction and were upregulated significantly more by KLF5KQ than by KLF5KR (SHH, WNT5A, IL11, and IL6), the induction of IL-11 was dependent on CXCR4 expression." (PMID 33731701, 2021). "We observed that the percentage of cells that were EGFP (IL-11)+ was increased in tumor tissues compared with nontumor colon tissues from AOM/DSS-treated Il11-Egfp reporter mice." (PMID 33863879, 2021). "Thus, it appears that colonic fibroblasts produced IL-11 in response to factors from tumor cells, which, in turn, activated and induced STAT3 phosphorylation in both IL-11+ and IL-11− colonic fibroblasts in an autocrine or paracrine manner." (PMID 33863879, 2021). "Since IL11 appears to be a direct target of MAFF while other gene regulation seems to be more cell type specific, we decided to focus on the role of MAFF-mediated IL11 expression in tumor cell invasion." (PMID 34262028, 2021). "Il11 and Egfp mRNA expression was elevated in tumor tissues compared with nontumor tissues from mice with AOM/DSS-induced CAC." (PMID 33863879, 2021). "We also found that the expression levels of Il11 and Egfp were elevated in the tumor tissues compared with non-tumor tissues in small intestine from ApcMin/+;Il11-Egfp reporter mice, and IHC revealed that IL-11+ fibroblasts appeared in the tumor tissues." (PMID 33863879, 2021). "Moreover, increasing evidence has indicated that LSS mediates tumour metastasis directly by acting on cytokines and their receptors in tumour cells, such as VEGF, IL11, and IGF-2." (PMID 32000836, 2020). "The study revealed that YTHDF2 inhibits HCC progression through m6A modification by decreasing the stability of interleukin 11 (IL11) and serpin family E member 2 (SERPINE2) mRNA, which are involved in tumor angiogenesis and inflammation activation respectively." (PMID 32733807, 2020). "Since IL11 is involved in migration and invasion in MDA-MB231 cells 31, our results suggest that it could be one of the key factors involved in tumor growth seen in our in vivo data." (PMID 32483202, 2020). "Notably, among the IL6 family members, also interleukin 11 (IL11), produced by TGF-β-stimulated CAFs, was found to play a role in tumor growth and distal metastasization in vivo." (PMID 32722560, 2020).
tumor (continued). "It has recently been shown that minor subclones expressing interleukin 11 (IL11) and vascular endothelial growth factor D (VEGFD) within the primary tumor can modulate the immune system in a manner that enhances polyclonal metastatic growth of otherwise non-metastatic clones." (PMID 31623163, 2019). "Since IL‐11 can activate STAT3 signaling and promote malignant phenotypes during tumor progression, we therefore reasoned that IL‐11 might be the mediator used by OLC8 to regulate STAT3 signaling." (PMID 31273847, 2019). "When tumor cells escape from the dormant state, they start to proliferate and secrete several factors, including the connective tissue growth factor (CTGF), interleukin-11 (IL-11), prostaglandin E (PGE2), and parathyroid hormone-related protein (PTHrP)." (PMID 31500357, 2019). "IL-11 promotes STAT3 activation and inflammatory cancer progression in an autocrine manner, while cancer cell-secreted serpin E2 confers invasive and metastatic processes by reprogramming the tumor vasculature." (PMID 31735169, 2019). "Moreover, multiple cell types upregulate IL11 transcript levels during CRC development, including hematopoietic cells, CAFs, and also tumor cells." (PMID 27148488, 2016). "Enhanced drive for expression of IL-6 and IL-11 may also be due to increased ligand driven EGFR activation, which also signal via STAT3, and which show increased expression during active tumour growth in the gp130757FF mouse." (PMID 24804649, 2014). "Therefore WP1066 inhibition of STAT3 activity and tumour progression was due in part to reduced polymophonuclear infiltration and reduced STAT3-dependent transcription of pro-inflammatory IL-6, IL-11, IL-1α, IL-1β and COX2 genes." (PMID 24804649, 2014). "It was of interest in the present study to investigate whether specifically IL11 regulated pSTAT3 and SOCS3 in cancer cells as both have been shown to be involved in numerous tumours." (PMID 20553623, 2010). "IL11 localised to leukocytes only in the advanced Grade 3 tumours and not in control postmenopausal endometrium." (PMID 20553623, 2010). "Conversely, IL‐11 knockdown did not affect tumor growth in NOD/SCID mice." (PMID 41178513, 2026). "The absence of IL‐11 significantly reduced the relative tumour growth in both mouse models." (PMID 40673604, 2025). "Multiple lines of transcriptomic evidence in tumor-educated THP1 cells point to STAT3 pathway activation, including upregulation of canonical STAT3 targets (SOCS3, CISH, BCL3, JUNB, PIM1) and increased expression of STAT3-activating ligands (IL6, IL11, LIF, OSM) in response to TNBC contact." (PMID 41514627, 2025). "As increases in circulating IL-11 levels may be independent of the tumor microenvironment, we performed immunohistochemistry for IL-11 protein confirmation in lung tumors and adjacent normal biopsies in two NSCLC patients." (PMID 39329890, 2024). "This suggests that the increased requirement for STAT3 signaling in tumor cells of KPT tumors, including the possible involvement of tumor cells that hitherto did not respond to IL-11, appears to be realized by the coordinated upregulation of IL-6 and its cognate IL-6Ra receptor subunit." (PMID 39128004, 2024). "In the absence of IL11 subclones, the tumour stroma collapses and so does the cancer." (PMID 38054591, 2023). "Because IL-11 plays a mediating role in cancer-related bone metastasis, researchers developed a ligand-targeted peptidomimetic drug, namely BMTP-11 (bone metastasis-targeting peptidomimetic-11), which binds to IL-11Rα in the tumor vascular endothelium of castrate-resistant prostate cancer patients." (PMID 38352248, 2023). "Il11, Il6, Ccl11, Mdk and Ptn have also been shown to play key roles in cancer progression and immune modulation, suggesting that altered expression of these genes in KPC-Cdh11+/- mice may contribute to changes in tumor immune profile." (PMID 37954069, 2023).